MUC1 (mucin 1, cell surface associated)
Diseases named in the same sentence as MUC1 in open-access papers (continued):
Sharing a sentence is not in itself a finding about the gene and the disease.
gastric cancer (continued). "At the same time, analysis of ferroptosis-related genes associated normal tissue and gastric cancer tissues screened out 19 FerDEGs: ten of them, i.e., TLR4, KRAS, HSF1, was highly expressed and nine of them, i.e., MUC1, PROM2, MT1G, were lowly expressed in tumor tissues." (PMID 36936437, 2023). "In the literature, an interaction between matrix metalloproteinases (MMPs) and MUC1 has not been found yet, but abnormal synthesis of MMPs is associated with a poor prognosis of patients with gastric cancer." (PMID 34770912, 2021). "Thus, our results revealing significant inhibition of Tn, T antigens, and their sialylated forms, enhanced by combined therapy, strongly support the rationality of potential anti-MUC1 application in gastric cancer treatment." (PMID 34206951, 2021). "Furthermore, MUC1 is overexpressed in breast, ovarian, lung, pancreatic, and prostate cancers and is a marker of poor prognosis in gastric cancer." (PMID 34638981, 2021). "Our studies confirmed that the combination of the chemotherapeutic agent with the monoclonal antibody against MUC1 could be a promising strategy in gastric cancer treatment with aberrant expression of MUC1, but further in vivo examinations will be required." (PMID 34770912, 2021). "Numerous previous evidence showed the association between MUC1 and the carcinogenesis of various tumor including gastric cancer; however, there was no expression of TRIM46 in the gastric mucosa." (PMID 34532288, 2021). "Much interest was placed on the role of MUC1 in gastric cancer development and progression." (PMID 34770912, 2021). "Several genetic risk loci of gastric cancer are known, ranging from the historically identified blood type A to the markers discovered through genome-wide association study, including prostate stem cell antigen (PSCA), mucin 1 (MUC1) and other genes." (PMID 34359626, 2021). "In addition, Genome-Wide Association Studies (GWAS) proposed genetic diversities like rs4072037G > A (5640G > A) in MUC1 gene and rs2294008C > T (5057C > T) polymorphisms in PSCA (Prostate Stem Cell Antigen) gene as genetic risk factors in gastric cancer." (PMID 32660489, 2020). "Lastly, as a mucin-type O-glycosylation it may be carried by a wide range of secreted glycoproteins that are overexpressed in gastric cancer such as MUC1 or CD44." (PMID 30189652, 2018). "MUC1 is a membrane-bound mucin, which plays an important role in the impairment of cell-cell adhesion, the immune response, and/or altered intracellular signaling, and is involved in the development and progression of gastric cancer." (PMID 27190429, 2016). "In conclusion, our meta-analysis suggests that MUC1 expression might be a marker of poor prognosis for survival in patients with gastric cancer, if detected by immunochemistry." (PMID 27190429, 2016). "Genetic variations in other genes (e.g. KDM5A, DNAH7, PLCE1, PSCA, PRKAA1, MUC1) reported to be specifically associated with gastric cancer initiation and progression were not investigated in the current study." (PMID 27929383, 2016). "They indicated that MUC1 was an independent prognostic indicator for gastric carcinoma." (PMID 27190429, 2016). "The funnel plots were all symmetrical, indicating that there was no publication bias in the studies of MUC1 polymorphism and gastric cancer association (Begg’s test: p= 0.115, Egger’s test: p= 0.060)." (PMID 25332893, 2014). "It was reported that HP infection upregulates MUC2, MUC5AC and MUC6 genes in KATO-III, a cultured gastric cancer cell line; however, it was demonstrated that HP infection reduced the rate of mucin turnover and decreased the levels of Muc1 in the gastric mucosa of mice." (PMID 24810688, 2014). "A large-sample-size Japanese study demonstrated that MUC1 rs4072037 was associated with gastric cancer risk in diffuse-type gastric cancer rather than intestinal-type gastric cancer." (PMID 25332893, 2014).
gastric cancer (continued). "Association of MUC1 rs4072037 and gastric cancer susceptibility was detected under all genotypic models without significant heterogeneity, suggesting decreased gastric cancer risk for individuals carrying the G allele." (PMID 25332893, 2014). "Our previous study showed that MUC1 expression in gastric cancers is a poor prognostic factor." (PMID 23152882, 2012). "Both MUC4 and MUC1 expression in the gastric cancers may be related with the poor prognostic factors, such as lymphatic invasion, venous invasion and lymph node metastasis, by means of different mechanism." (PMID 23152882, 2012). "We reported that MUC1 expression was high in the well differentiated adenocarcinoma in gastric cancers including advanced cancers, and the high MUC1 expression may affect the survival of patients with well differentiated adenocarcinoma of stomach." (PMID 23152882, 2012). "In the present study, we examined the expression profiles of MUC4 as well as MUC1 in early gastric cancer tissues, and found that MUC4 and MUC1 expression in the early gastric cancers would become poor prognostic factors by lymph vessel invasion, blood vessel invasion and lymph node metastasis." (PMID 23152882, 2012). "Therefore, MUC1 should be further studied to better clarify its potential as a novel therapeutic target for gastric cancer." (PMID 22073229, 2011). "The role of MUC1 in gastric cancer progression remains to be clarified." (PMID 22073229, 2011). "High MUC1 expression is related to poor prognosis and carcinogenesis in gastric cancer." (PMID 21931799, 2011). "We downregulated MUC1 expression in a gastric carcinoma cell line by RNA interference and studied the effects on cellular proliferation (MTT assay), apoptosis (TUNEL assay), migration (migration assay), invasion (invasion assay) and aggregation (aggregation assay)." (PMID 22073229, 2011). "In a study on the association of allotypes with antibodies against MUC1, a tumor-associated antigen, gastric cancer patients with the phenotype Gm3 23 5, 13 had lower anti-MUC1-IgG levels compared to patients without this phenotype." (PMID 21187010, 2010). "Similar expression patterns have been found for Muc1 gene that is highly expressed in gastric carcinoma and proposed to be involved in gastric carcinogenesis as well as for the genes Cckar, Ggh and Ang that were reported to be implicated in the genesis of various tumours." (PMID 19799787, 2009). "That is, ADAM17 mediated MUC1 shedding induced by H. pylori infection may have caused increased expression of MUC1 as a coping mechanism although it failed to prevent gastric cancer development." (PMID 39755747, 2025). "Moreover, RA inhibits the protein level of MUC1 mucin in gastric cancer." (PMID 37836581, 2023). "Thus, the assessment of MUC1 on the endoscopic biopsy specimen of gastric cancer might be a useful marker when ESD is considered a primary treatment for early gastric cancer." (PMID 36831343, 2023). "However, MUC1 also plays a relevant role in the development and progression of gastric cancer." (PMID 34770912, 2021). "Missing information may reflect “negative” or more conservative association of MUC1 with clinicopathological parameters that could reduce the significance of MUC1 expression as a predictor of outcome in gastric cancer." (PMID 27190429, 2016). "However, little is known about the influence of MUC1 on cell apoptosis in gastric carcinoma cells." (PMID 22073229, 2011). "Another study demonstrated reduced levels of IgG and IgM antibodies against TF and MUC1 antigens in gastric cancer (GC) patients compared with healthy donors, though notably, the median age of the patients (65 years) differed significantly from that of the donors (51 years)." (PMID 41596448, 2026). "Salicylate inhibited KAT8 expression, reduced H4K16ac in the mucin 1 (MUC1) promoter, downregulated AKT phosphorylation, and suppressed EMT in gastric cancer cells." (PMID 40508066, 2025).
gastric cancer (continued). "Mucin 1 (MUC1) is a transmembrane glycoprotein that is overexpressed and aberrantly glycosylated in various cancers, including gastric cancer." (PMID 40940995, 2025). "MUC1 and MUC5AC can enhance the proliferative, invasive, and metastatic properties of ovarian and gastric cancers by regulating the E‐cadherin and β‐catenin." (PMID 37666495, 2024). "For example, enhanced expression of miR-29a can inhibit mucin 1 (MUC1), reducing the expression levels of cell cycle-dependent kinases CDK2, CDK4, and CDK6, leading to reduced proliferation of gastric cancer cells." (PMID 39519347, 2024). "Studies have indicated that antigens like HER2, CEA, MUC1, Claudin 18.2 (CLDN 18.2), EpCAM, B7H3, MSLN, and NKG2D serve as effective targets for CAR-T cell therapy in gastric cancer." (PMID 38622705, 2024). "According to the previous studies performed with AGS gastric cancer cells, we have established IC50 for anti-MUC1 as below 5 μg/mL and for tiliroside as far less than 160 μM." (PMID 37685842, 2023). "In our study, we decided to assess the efficacy of the combined action of anti-MUC1 monoclonal antibody and tiliroside in AGS gastric cancer cells." (PMID 37685842, 2023). "In early gastric cancer (EGC), patients with a high level of MUC1 expression showed a higher rate of lymphovascular invasion (71.4% vs. 21.4%; p = 0.026) and EGC meeting non-curative resection (85.7% vs. 42.9%; p = 0.061) than those with negative MUC1." (PMID 36831343, 2023). "In this study, we aim to assess the effect of the combined action of anti-MUC1 and tiliroside on some cancer-related factors in AGS gastric cancer cells." (PMID 37685842, 2023). "MUC1-Tn CAR-modified Vγ9Vδ2 T cells exhibited similar or stronger anti-tumor effect against breast cancer cell and gastric cancer cell in vitro compared with CAR-αβT cells." (PMID 35747139, 2022). "In gastric cancer, miR-206 can directly bind to the 3′ UTR of MUC1 and inhibit the expression of MUC1, thereby suppressing proliferation, migration, and invasion and inducing apoptosis." (PMID 35154471, 2022). "Several antigens expressed by gastric cancer cells have been identified: human epidermal growth factor receptor 2 (HER2), mucin 1 (MUC1), carcinoembryonic antigen (CEA), claudin 18.2 (CLDN18.2), and mesothelin (MSLN)." (PMID 36291891, 2022). "Our purpose was to assess its influence on apoptosis, Bax, caspases, MUC1, cancer-related carbohydrate antigens, enzymes participating in their formation, and galectin-3 in AGS gastric cancer cells." (PMID 34681197, 2021). "We also proved that the anti-MUC1 antibody with OM-86II decreased the concentrations of MMP-9, sICAM1 and mTOR in gastric cancer cells." (PMID 34770912, 2021). "Mucin 1 (MUC1) is a member of the mucin family (MUC1–MUC21) and plays different roles in normal and gastric cancer cells." (PMID 34770912, 2021). "In this study, we demonstrated the effects of combined action of an anti-MUC1 monoclonal antibody with cisplatin and two pyrazole-platinum complexes on apoptosis and cell death-related factors in CRL-1739 gastric cancer cells." (PMID 34206951, 2021). "Genome-Wide Association Studies (GWAS) have shown that genetic diversities MUC1 (Mucin 1) and PSCA (Prostate Stem Cell Antigen) genes are involved in gastric cancer." (PMID 32660489, 2020). "Similar to MUC1, COX-2 has been shown to stimulate innate immune responses and oncogenic signaling that drives gastric cancer initiation and progression." (PMID 31941061, 2020). "The expression of MUC1 in the MKN74 and NCI-N87 gastric spheroids is located at the formed glandular-like structures, resembling the phenotype observed in differentiated gastric-cancer tissue." (PMID 30380716, 2018). "MUC1, a member of the mucin family, is expressed in tumors of various human organs and may function as an antiadhesion molecule that inhibits cell-to-cell adhesion, inducing tumor metastasis, and served as a potential biomarker of tumor progression in early gastric cancer." (PMID 27190429, 2016).
gastric cancer (continued). "Moreover, MUC1 rs4072037 T>C may lead to splicing alteration, whereas, PLCE1 rs2274223 A>G may cause an Arg-to-His change that were significantly associated with risk of stomach cancer in the initial scanning phase." (PMID 25658482, 2015). "In conclusion, in the present study of early gastric cancers, MUC4/8G7, MUC4/1G8 and MUC1/DF3 expressions were observed mainly in well differentiated adenocarcinomas." (PMID 23152882, 2012). "The work presented here shows for the first time that MUC1 expression influences proliferation, apoptosis and cell-cell aggregation of MKN45 gastric carcinoma cells." (PMID 22073229, 2011). "Mucin genes expressed in normal gastric mucosa include MUC1, MUC5AC and MUC6, whereas MUC2 is expressed aberrantly in 30% of gastric carcinomas." (PMID 18000536, 2007). "CK-18 was expressed in eight (73%) of 11 lymph nodes containing gastric cancer metastasis, CEA in seven (64%), hTRT in six (55%), and MUC-1 in six (55%)." (PMID 12915877, 2003). "MUC1 and MUC2 are already well known to be overexpressed in gastric cancers, however, MUC13, a transmembrane mucin, might play an as-yet-unknown role in cell signaling and epithelial barrier protection." (PMID 39910169, 2025). "Similarly, MUC1 (CD227), a transmembrane glycoprotein commonly overexpressed in breast and gastric cancers, facilitates immune evasion by disrupting cell adhesion and promoting immunosuppressive signaling pathways." (PMID 41154585, 2025). "Other targets that entered clinical trials of gastric cancer primarily included HER2 (NCT04660929), CEA (NCT05396300), MUC1 (NCT05239143), EpCAM (NCT05028933, NCT03563326), MSLN (NCT03941626), EGFR (NCT03740256), B7H3 (NCT04864821) and NKG2DL (NCT04550663), with no conclusions reported yet." (PMID 38622705, 2024). "The amount of the transmembrane mucin called mucin 1 (MUC1) in plasma from healthy controls (HCs) and patients with colorectal, pancreatic, and gastric cancer with or without venous thromboembolism was measured." (PMID 39061213, 2024). "Although the findings suggest the role of MUC1 as a prognostic marker for gastric cancer, the expression and prognostic value of MUC1 have not been studied in US patients with gastric cancer." (PMID 36831343, 2023). "Patients with high level of MUC1 expression had a two-fold increase in the proportion of early gastric cancer categorized as non-curative resection (85.7% vs. 42.9%) compared to those without MUC1 expression." (PMID 36831343, 2023). "By contrast, the expression level of MUC1 in colon cancer and gastric cancer apparently did not correlate with any clinicopathological parameter but still is an independent marker of prognosis." (PMID 34386419, 2021). "We conducted a case-control study comprising 116 patients with gastric cancer as well as 102 sex- and age-matched controls and confirmed that the SNPs MUC1 (mucin 1) rs9841504 and ZBTB20 (zinc finger and BTB domain containing 20) rs4072037 were associated with an increased gastric cancer risk." (PMID 27127881, 2016). "More interestingly, whereas MUC1 rs4072037, ZBTB20 rs9841504, and TYMS rs2790 were suggested to improve the risk of noncardia gastric cancer (mainly the diffuse type) by 5- to 8-fold (P < 0.05*)." (PMID 27127881, 2016). "Downregulation of MUC1 expression was found to increase proliferation and apoptosis in MKN45 gastric carcinoma cell line, but in vivo study showed that mice injected with MUC1 downregulated cells developed smaller tumors when compared to those injected with the control cells." (PMID 26367866, 2015). "Nonetheless, the relevance of MUC1 in gastric cancer progression has not been previously investigated." (PMID 22073229, 2011). "Patients with gastric cancer had higher levels of MUC1 IgG abs than blood donors (p < 0.001) irrespective of H. pylori serologic status or stage of disease." (PMID 24212946, 2011).
gastric cancer (continued). "In vivo assays were also performed in mice, in order to study the tumorigenicity of cells with and without MUC1 downregulation in MKN45 gastric carcinoma cell line." (PMID 22073229, 2011). "We assessed the presence of micrometastases in SNs of gastric cancer by using multiple-marker RT–PCR and Southern blot assay with the markers CK-18, CEA, hTRT, and MUC-1." (PMID 12915877, 2003). "However, there are contradictory results in some studies showing that MUC1 was not an independent factor for the prognosis of patients with gastric carcinoma." (PMID 39886661, 2024). "A high level of MUC1 expression is associated with the presence of lymphovascular invasion and a high possibility of non-curative resection after ESD in patients with early gastric cancer." (PMID 36831343, 2023). "According to the ESD criteria for early gastric cancer, the rate of non-curative resection was 85.7% (six of the seven patients) in patients with a high level of MUC1 expression and 42.9% (six of the fourteen patients) in those without MUC1 expression (p = 0.061)." (PMID 36831343, 2023). "Emerging evidence has shown that MUC1 and TFF2 play crucial roles in the H. pylori-infected pathogenesis of gastric cancer (GC)." (PMID 32122390, 2020). "These researches suggested that MUC1 did not affect the progression of human gastric cancer." (PMID 27190429, 2016). "In addition, MUC1 positive gastric cancer patients also displayed lower 5-year survival rate than MUC1 negative ones." (PMID 27190429, 2016). "It remains to be investigated whether all mucins (MUC1, MUC2, MUC4, MUC 5AC, MUC 5B, MUC6 etc.) may carry these sialylated and sulfated oligosaccharidic sidechains detected in intestinal metaplasia, gastric carcinoma and cholelithiasis." (PMID 17565665, 2007). "Most of the other colorectal and gastric cancer markers such as CDX2, MUC1, MUC2, and MUC6 were also negative." (PMID 34397857, 2021). "We proved that our tested combination of OM-86II with the anti-MUC1 antibody reduced only MMP-9, but not MMP-2 concentration in AGS gastric cancer cells." (PMID 34770912, 2021). "Gastric cancer cells grown in monolayer do not express mucins, but gastric MCTS showed expression of the MUC1 mucin, as detected by two different monoclonal antibodies." (PMID 30380716, 2018). "Also in the present study of the gastric cancers in the early stage, there was no siginificant correlation between expression of MUC4 and MUC1." (PMID 23152882, 2012).